PCLAF (PCNA clamp associated factor)
Description:
PCNA-binding protein that acts as a regulator of DNA repair during DNA replication. Following DNA damage, the interaction with PCNA is disrupted, facilitating the interaction between monoubiquitinated PCNA and the translesion DNA synthesis DNA polymerase eta (POLH) at stalled replisomes, facilitating the bypass of replication-fork-blocking lesions. Also acts as a regulator of centrosome number.
Synonyms: OEATC-1; PAF15; p15PAF; KIAA0101; NS5ATP9; PAF; L5; p15(PAF); OEATC; OEATC1; p15/PAF
Tractability: PROTAC: UniProt records ubiquitination sites on it; ubiquitination databases record sites on it.
Target class: Other nuclear protein
Gene: Protein-coding gene on chromosome 15 (64,364,304 to 64,387,687, reverse strand). Ensembl gene ENSG00000166803.
Subcellular location: Nucleus; Cytoplasm, perinuclear region
Subcellular location (Human Protein Atlas): Centrosome
Pathways (Reactome):
DNA Repair: Termination of translesion DNA synthesis
Gene Ontology:
Molecular function: chromatin binding; molecular adaptor activity; protein binding
Biological process: centrosome cycle; DNA damage response; DNA replication; regulation of cell cycle; response to UV; translesion synthesis
Cellular component: centrosome; nucleus; perinuclear region of cytoplasm; nucleoplasm
Genetic constraint (gnomAD): Loss-of-function variants: 8 observed, 12.81 expected, observed/expected ratio (o/e) 0.62, 90% interval 0.37 to 1.13. The upper end of that interval is the gene's LOEUF score, 1.13, which puts it in group 4 of 6, group 1 being the genes least tolerant of losing a copy. Missense variants: 100 observed, 120.67 expected, observed/expected ratio (o/e) 0.83, 90% interval 0.7 to 0.98. Synonymous variants: 30 observed, 43.29 expected, observed/expected ratio (o/e) 0.69, 90% interval 0.52 to 0.94.
Homologues: Orthologues: macaque PCLAF (97% identical), dog PCLAF (91% identical), chimpanzee PCLAF (89% identical), guinea pig PCLAF (88% identical), mouse Pclaf (85% identical), pig PCLAF (85% identical), rat Pclaf (77% identical), rat LOC100363428 (69% identical), tropical clawed frog pclaf (54% identical), zebrafish pclaf (45% identical).
Diseases named in the same sentence as PCLAF in open-access papers:
PCLAF is named in the same sentence as 61 diseases in open-access papers, as found by Europe PMC text mining. Sharing a sentence is not in itself a finding about the gene and the disease. The quoted sentences say what the papers report.
breast carcinoma (17 papers, 2012 to 2023). "PCLAF and ISG15 overexpression are associated with poor prognosis of breast cancer, and DTL knockdown decreases breast cancer cells’ proliferation and metastasis." (PMID 33662042, 2021).
hepatocellular carcinoma (12 papers, 2006 to 2025). A malignant tumor that arises from hepatocytes. "KIAA0101 is overexpressed in various solid tumors, but few studies have directly investigated the expression of KIAA0101/PCLAF in hepatocellular carcinoma (HCC), and these studies have reported contradictory results." (PMID 33743635, 2021). "Studies have confirmed that overexpression of PCLAF in adrenal cortical tumors, nasopharyngeal carcinoma, and hepatocellular carcinoma may promote the growth and invasion of cancer cells." (PMID 34539726, 2021). "KIAA0101/PCLAF is overexpressed in various cancers, including hepatocellular carcinoma (HCC)." (PMID 33743635, 2021).
lung cancer (9 papers, 2016 to 2022). A malignant neoplasm involving the lung. "A recent paper has highlighted the key role of PAF (PCLAF) in modulating gene expression patterns and G1/S progression controlled by the DREAM complex in lung cancer." (PMID 35210406, 2022).
lung adenocarcinoma (6 papers, 2020 to 2023). A carcinoma that arises from the lung and is characterized by the presence of malignant glandular epithelial cells. "Proliferating cell nuclear antigen binding factor (encoded by KIAA0101/PCLAF) regulates DNA synthesis and cell cycle progression; however, whether the level of KIAA0101 mRNA in lung adenocarcinoma is related to prognosis and tumor immune infiltration is unknown." (PMID 33231570, 2020).
neuroblastoma (3 papers, 2022 to 2025). Neuroblastoma (NB) is the most common solid, extracranial childhood tumor. "At the same time, PCLAF expression was correlated with age at diagnosis, histological type, Shimada pathological type, risk grade, and clinical stage, and OS and EFS with high PCLAF expression were worse in neuroblastoma databases." (PMID 35210406, 2022). "PCLAF is extremely overexpressed in neuroblastoma and is associated with poor prognosis." (PMID 35210406, 2022). "Four prognostic genes (CNR1, PRKACB, CDKN3, and PCLAF) were identified, and a prognostic model based on these genes was developed that provides novel insights into the prognostic evaluation of neuroblastoma." (PMID 40302936, 2025). "CNR1, PRKACB, CDKN3, and PCLAF were found to significantly affect the overall survival and event-free survival of neuroblastoma patients and were positively correlated with the INSS advanced stages." (PMID 40302936, 2025). "The model containing CNR1, PRKACB, CDKN3, and PCLAF can serve as a new prognostic biomarker for predicting the prognosis of patients with neuroblastoma." (PMID 40302936, 2025). "Since the DREAM complex (B-MYB, FOXM1) have previously been shown to be essential for neuroblastoma cell proliferation and survival, this further suggests that PCLAF plays an important role in neuroblastoma cell proliferation and survival." (PMID 35210406, 2022). "Finally, both the mRNA and protein expression verification assays demonstrated that the CDKN3 and PCLAF were upregulated, while the PRKACB was downregulated in advanced-stage neuroblastoma tissue samples." (PMID 40302936, 2025). "The decrease in PCLAF gene expression significantly downregulated CyclinA2, CyclinB1, CyclinD1, CyclinE2, CDK2, and CDK6, which further showed that downregulation of PCLAF can inhibit the proliferation of neuroblastoma." (PMID 35210406, 2022).
COVID-19 (2 papers, 2022 to 2025). A disease caused by infection with severe acute respiratory syndrome coronavirus 2. "Another study found immature myeloid cell populations in the peripheral blood of critically ill COVID-19 patients, among which the monocytoid precursors highly expressed the cell cycle gene PCLAF." (PMID 36551164, 2022). "Previous studies have found that PCLAF is a potential key gene for COVID-19, and its expression is down-regulated in COVID-19 infected human cell lines." (PMID 36551164, 2022). "KIF2C and PCLAF have been identified as critical genes in COVID-19 and may be potential biomarkers and treatment targets." (PMID 41000417, 2025).
glioblastoma (2 papers, 2023 to 2025). The most malignant astrocytic tumor (WHO grade IV). "The analysis indicated that glioblastoma patients exhibiting genomic alterations in PCNA clamp-associated factor (PCLAF), RRM2, nucleolar and spindle-associated protein 1 (NUSAP1), and KIF23 displayed reduced overall survival rates, as shown in Fig.." (PMID 39248068, 2025).
prostate carcinoma (2 papers, 2020 to 2025). A carcinoma that arises from epithelial cells of the prostate gland. "However, CD10, KHDRBS3, PCLAF, PSMA, SIK2 and GDF15 were differentially expressed with prostate cancer progression." (PMID 39578642, 2025).
pulmonary fibrosis (2 papers, 2019 to 2022). Chronic progressive interstitial lung disorder characterized by the replacement of the lung tissue by connective tissue, leading to progressive dyspnea, respiratory failure, or right heart failure. "PCLAF was also proven to be highly expressed in PBMC in the familial pulmonary fibrosis patients, and it is related to the immune system dysregulation, which may further lead to pulmonary fibrosis." (PMID 36551164, 2022).
melanoma (1 paper, 2025). A malignant, usually aggressive tumor composed of atypical, neoplastic melanocytes. "As could be seen from the figure, C2 PHLDA2+ Melanoma cells and C4 PCLAF+ Melanoma cells had the highest expression on the ARGN signaling pathway." (PMID 39781353, 2025). "Additionally, we found that the TGFb signaling pathway only targets the C4 PCLAF+ Melanoma cells and C2 PHLDA2+ Melanoma cells subgroup, which suggests that this pathway plays an important role in the C4 subgroup." (PMID 39781353, 2025). "Regarding the nomenclature of C4 PCLAF+ Melanoma subtype, previous research suggests that PCLAF, also recognized as PAF15/KIAA0101, is a nucleoprotein with a molecular weight of 15 kDa." (PMID 39781353, 2025).
myeloid leukemia (1 paper, 2021). A clonal proliferation of myeloid cells and their precursors in the bone marrow, peripheral blood, and spleen. "The KIAA0101/PCLAF gene was first cloned and sequenced from cDNA libraries of the immature myeloid leukemia cell line KG-1." (PMID 33743635, 2021).
tumor (47 papers, 2006 to 2025). "In an investigative study to elucidate the role of Curcumin, it was observed that Curcumin induces the expression of miR-30a-5p, a well-known tumor suppressor, which is inversely correlated with the expression of PCNA clamp-associated factor (PCLAF)." (PMID 37895357, 2023). "PCLAF (PCNA clamp-associated factor), also known as PAF15/ KIAA0101, is overexpressed in most human cancers and is a predominant regulator of tumor progression." (PMID 35210406, 2022). "Through scRNA-seq, we identified the C2 PCLAF+ subtype in GBM and analyzed its molecular characteristics and functional role in tumor progression." (PMID 40787449, 2025). "This work clarifies GDF15’s critical function in fibroblast–tumor cell interactions in 3 key ways: First, GDF15 promotes the growth and invasion of HNSCC cells by up-regulating PCLAF expression via IRF5." (PMID 41035818, 2025). "Myeloid cells were subclustered into monocyte, Tumor-associated macrophage (TAM) including SPP1+ TAM, C1Qs+TAM, HSPs+ TAM, ACP5+ TAM, and CCL5+ TAM, classical dendritic cell (cDC) encompassing cDC, CD1A+ DC, LAMP3+ DC and PCLAF+ DC, plasmacytoid DC (pDC) as well as unknown subpopulations." (PMID 40904511, 2025). "In ST 1 slide, MIA and TransferData analysis demonstrated the unique spatial distribution pattern of C2 PCLAF+ subtype in GBM tissue, suggesting that this subtype might establish specific tumor niches to promote recurrence and drug resistance." (PMID 40787449, 2025). "However, CD10, KHDRBS3, PCLAF, PSMA, SIK2 and GDF15 were differentially expressed with PCa progression, emphasising their roles in promoting tumour growth, invasion and metastasis." (PMID 39578642, 2025).
cancer (41 papers, 2006 to 2025). A tumor composed of atypical neoplastic, often pleomorphic cells that invade other tissues. "In addition, PCLAF is involved in DNA damage repair by interacting with proliferating cell nuclear antigen, which is advantageous for cancer cells’ resistance and survival in genotoxic treatments like radiation and chemotherapy." (PMID 41035818, 2025).
PCLAF also shares sentences with these, for which no sentence is quoted: pancreatic cancer (9 papers); non-small cell lung carcinoma (8); colon carcinoma (7); gastric cancer (6); glioma (5); liver cancer (4); nasopharyngeal carcinoma (4); adenocarcinoma (3); invasive ductal carcinoma (3); ovarian carcinoma (3); renal cell carcinoma (3); adrenocortical tumor (2); chronic lymphocytic leukemia (2); colorectal cancer (2); esophageal cancer (2); esophageal squamous cell carcinoma (2); kidney cancer (2); lung squamous cell carcinoma (2); rectal cancer (2); renal carcinoma (2); thyroid cancer (2); Adrenal Cancer (1); adrenal cortical tumors (1); anaplastic thyroid cancer (1); anemia (1); benign tumors (1); bladder carcinoma (1); breast tumors (1); Cirrhosis (1); fibrosarcoma (1).
A further 18 diseases each share a sentence with PCLAF in 1 paper.